S1PR1 (sphingosine-1-phosphate receptor 1)
Diseases named in the same sentence as S1PR1 in open-access papers (continued):
Sharing a sentence is not in itself a finding about the gene and the disease.
lymphopenia (34 papers, 2013 to 2026). Reduction in the number of lymphocytes. "Single disruption of Jmjd3 or Utx had partial effects on S1pr1 expression in mature OT-II thymocytes, and caused a combination of thymocyte accumulation and lymphopenia, similar to but less marked than in dKO mice." (PMID 26328764, 2015). "Delayed lymphopenia has been reported in mice with a knock-in mutation of the S1PR1 serine-rich C-terminal motif." (PMID 24358210, 2013). "Furthermore, treating moesin-deficient mice with FTY720, an S1P receptor agonist known to internalize S1PR1, caused delayed lymphopenia, and lymphocytes isolated from FTY720-treated moesin-deficient mice still responded to S1P ex vivo in chemotaxis assays." (PMID 24358210, 2013). "Pharmacological stabilization of S1PR1 on the T cell surface has been suggested as a potential strategy to ameliorate bone marrow T cell sequestration and reverse baseline lymphopenia." (PMID 38390330, 2024). "Both drugs mainly induce peripheral lymphopenia by binding to S1PR1, which renders lymphocytes unable to respond to the S1P gradient." (PMID 36430692, 2022). "Studies of S1PR1 knockout mice in hematopoietic cells reported significant lymphopenia, resulting from intact lymphocyte maturation but the inability of the last to egress from thymus and peripheral lymphoid organs." (PMID 34831439, 2021). "As the S1P/S1PR1 axis is known to be crucial for lymphocytes migration from the secondary lymphoid nodes, S1PR1 internalization leads to a general lymphopenia, which, in turn, reduces the T-cells infiltration in the CNS." (PMID 33066042, 2020). "S1PR1 deficiency results in blocked lymphocyte egression, a condition known as lymphopenia, suggesting a vital role for S1PR1 in the timely and appropriate distribution of immune cells, a process that aids homeostasis of the immune system." (PMID 31293578, 2019). "The immunosuppressive drug FTY720 efficiently induces S1PR1 internalization and its subsequent degradation, thus preventing lymphocyte egress from lymphoid organs and inducing profound lymphopenia." (PMID 24358210, 2013). "Agonist-induced S1PR1 internalization was delayed in T cells expressing the mutant S1PR1, suggesting that defective S1PR1 internalization leads to delayed lymphopenia." (PMID 24358210, 2013). "The immunosuppressant FTY720 is phosphorylated in vivo to function as an S1P receptor agonist and to down-regulate S1PR1, and is therefore thought to induce lymphopenia by sequestering lymphocytes in lymphoid organs." (PMID 24358210, 2013). "FTY720P blocks lymphocyte egress from lymphoid organs and induces profound lymphopenia, primarily by inducing lymphocytes to internalize and degrade S1PR1." (PMID 24358210, 2013). "However, currently approved S1PR1 modulators such as fingolimod are hindered for this indication as they induce lymphopenia." (PMID 42310852, 2026). "Global Spns2 KO mice phenocopy S1pr1 KO mice and exhibit a block in thymic egress and lymphopenia." (PMID 29333002, 2017). "S1PR1 contribute lymphopenia and mediate cardioprotective effect." (PMID 28596734, 2017). "However, sustained lymphopenia triggered by S1PR1 antagonism may rather by disadvantageous, since T cells are needed for immunity." (PMID 31357710, 2019). "However, in the case of cancer therapy, as well as during infection, sustained lymphopenia triggered by S1PR1 antagonism may rather be disadvantageous, since T cells are needed at the tumor site for a proper anti-tumor response." (PMID 31379883, 2019). "By limiting S1PR1 expression, FTY720 inhibits the lymphocyte egress from lymphoid organs, leading to lymphopenia, which is the core of its therapeutic effect in MS." (PMID 34831439, 2021). "Based on the observed lymphopenia in these models, SEW2871 acted as a functional S1PR1 antagonist as expected." (PMID 31379883, 2019).
lymphopenia (continued). "Moreover, we showed that FTY720-induced lymphopenia is delayed in moesin-deficient mice, and that T cells from FTY720-treated moesin-deficient mice respond to S1P in chemotaxis assays, indicating that the loss of moesin causes an S1PR1 internalization defect in vivo." (PMID 24358210, 2013). "To investigate the influence of lymphocyte circulation in PP size reduction after antibiotic treatment, we used the S1PR1 functional antagonist FTY720, which effectively halts lymphocyte circulation through LNs and PPs due to conjunctional effects of systemic egress blockade and lymphopenia." (PMID 41403930, 2025). "However, lymphopenia was not the reason for protection as mice, harboring a selective S1PR1 knockout in proximal tubule cells, were protected as well." (PMID 31379883, 2019).
autoimmune disease (29 papers, 2012 to 2025). A disorder resulting from loss of function or tissue destruction of an organ or multiple organs, arising from humoral or cellular immune responses of the individual to their own tissue constituents. "Due to the central role of S1P in lymphocyte transport, S1PR1 has been implicated in autoimmune diseases and cancer." (PMID 37446355, 2023). "S1P signaling primarily mediated by S1PR1 contributed a pivotal role in vascular stability, permeability, and several diseases including autoimmune disease and inflammation." (PMID 41326489, 2025). "S1PR1 is involved in autoimmune diseases by directly or indirectly acting on STAT3 to activate downstream signaling pathways." (PMID 37858140, 2023). "S1PR1 is involved in the development of various immune cells, mediates lymphocyte migration, and is abnormally expressed in various autoimmune diseases." (PMID 37858140, 2023). "Multiple drugs that inhibit S1PR1 function are in use clinically for the treatment of autoimmune diseases." (PMID 36824756, 2023). "Their research indicates that lymphocyte reduction can establish the background for a selective S1PR1 modulator in multiple chronic and autoimmune diseases: for example, psoriasis." (PMID 37834321, 2023). "ACT-209905, a chiral amino pyridine derivative of ponesimod, is an S1PR1 modulator with immunomodulating properties that could be of use in treating autoimmune diseases." (PMID 37686550, 2023). "FTY720, a functional antagonist of S1PR1 that is used extensively to treat patients with autoimmune disease, induces naive T cell death via the same pathway as genetic deletion of SPNS2 and S1PR1." (PMID 38194271, 2024). "While there is scant information about the roles of S1P/S1PR1 signaling in adult lymphatic vasculature, our findings lay a groundwork for future studies of S1PR1-mediated LEC phenotype regulation in homeostatic processes and inflammatory/autoimmune diseases." (PMID 32091396, 2020). "Importantly, several S1PR1 modulators (e.g. Fingolimod, also known as FTY720, Siponimod, Ozanimod, and Etrasimod), have been approved for treating the autoimmune diseases multiple sclerosis and ulcerative colitis." (PMID 37039481, 2023).
glioblastoma (23 papers, 2013 to 2025). The most malignant astrocytic tumor (WHO grade IV). "This work is based on our previously published finding that S1PR1 expression is strongly up-regulated in human glioblastoma samples and the fact that there is an association between S1PR1 with patients’ survival times." (PMID 37686550, 2023). "However, analysis of fresh human glioblastoma tissues from 117 patients who underwent surgical resections revealed that S1PR1 expression was associated with extended patient survival, while high S1PR2 expression was linked to a poorer survival outcome." (PMID 38894892, 2024). "Recently, it has been shown that glioblastomas may cause sequestration of T cells in bone marrow via T-cell internalization of S1PR1, and enforced expression of S1PR1 in combination with T-cell activation via 4-1BB agonism can increase survival in vivo." (PMID 34222022, 2021). "Downregulation of S1PR1 expression has been shown to increase proliferative activity resulting in enhanced malignancy and poor survival of glioblastomas while high-level expression of transcripts encoding ephrin-B2 has been reported as predictive of favourable disease outcome of neuroblastoma." (PMID 23526956, 2013). "The authors suggest that S1PR1 alone is insufficient for a maximum S1P-induced response in the glioblastoma cell lines." (PMID 38894892, 2024). "S1PR1 overexpression significantly induced the expression and activity of urokinase plasminogen activator (uPA) and, thus, cell invasion in glioblastoma multiforme." (PMID 36361531, 2022). "S1PR1 overexpression, which contributes to the expression and activity of urokinase plasminogen activator (uPA), significantly expedites invasion in glioblastoma." (PMID 31807117, 2019). "S1PR1–5 and S1P metabolic enzymes are found in three different human glioblastoma cell lines and S1P has wide-ranging effects on glioblastoma cell migration." (PMID 31807117, 2019). "The expression of S1PR2 by glioblastoma cells may be explained by their requirement to balance the input from other expressed S1P receptor subtypes, such as S1PR1 or S1PR3." (PMID 31062076, 2019). "A combination therapy for glioblastoma should also target the NLRP3 inflammasome pathway, which induces tumor metastasis in response to S1P/S1PR1 and C3 complement signaling." (PMID 38894892, 2024). "Nonetheless, in the U-118 MG and U-373 MG human glioblastoma cell lines, both S1PR1 and S1PR3 concurrent expression promote the motility and invasiveness of glioblastoma cells through overlapping but distinct mechanisms in vitro." (PMID 38894892, 2024). "The human cytomegalovirus-encoded G protein-coupled receptor (GPCR), US28, was reported to promote U251 glioblastoma malignancy by stimulating SPHK1 function to release more S1P, which signals via S1PR1 using in vitro assays." (PMID 38894892, 2024). "In this paper, we report on the inhibition of glioblastoma (GBM) cell growth and migration by the putative S1PR1 modulator ACT-2009905, using appropriate in vitro models." (PMID 37686550, 2023). "In turn, in an autocrine/paracrine manner, the extracellular S1P stimulates glioblastoma cell growth and GEC migration and tubule formation in a S1PR1/S1PR3-dependent trend." (PMID 35326565, 2022). "In glioblastoma multiforme (GBM), one of the brain tumors with worse prognosis, increased expression of S1PR1 and S1PR2 correlated with decreased patient’s survival." (PMID 27800303, 2016). "The SPHKI/S1P/S1PR1 signaling activates AKT, JAK2/STAT3, and cMYC and enhances the levels of the cancerous inhibitor of protein phosphatase 2A (CIP2A) downstream to promote the pro-survival phenotype in glioblastoma cells." (PMID 38894892, 2024). "Interestingly, S1PR1 and S1PR2 pointed out high expression levels in patients with glioblastoma multiforme (GBM)." (PMID 38419070, 2024). "Thus, a putative S1PR1 modulator, ACT-209905, inhibits the growth and migration of human and mouse glioblastoma cell lines in vitro." (PMID 38894892, 2024).
glioblastoma (continued). "Unlike S1PR4, S1PR1,2,3, and 5 have been reported to be expressed in glioblastoma cells and regulate S1P signaling with context-dependent effects on tumor progression." (PMID 38894892, 2024). "Blockade of S1PR1 is commonly employed using the sphingosine analog fingolimod to reduce immune trafficking in multiple sclerosis; fingolimod may also inhibit ceramide synthases, SK1, and SPL and was proposed as a possible therapeutic for glioblastoma." (PMID 34222022, 2021). "A small trial of fingolimod was initiated with the aim of assessing whether sequestration of lymphocytes via S1PR1 antagonism could reduce post-chemoradiation lymphopenia in glioblastoma patients, but results have not yet been published (NCT02490930)." (PMID 34222022, 2021).
colitis (20 papers, 2014 to 2026). Inflammation of the colon. "In contrast, chronic activation of S1PR1 by S1P, the product of sphingosine kinase 1 (SphK1) in colitis‐associated cancer increases the risk for colon cancer." (PMID 27239439, 2016). "Previously, we found that injection of intra-submandibular glands with S1P resulted in the maintenance of homeostasis in the epithelial structure through the S1pr1/eNOS axis, which plays a vital role in the pathogenesis of colitis." (PMID 40761802, 2025). "Previous studies revealed elevation of S1P production and S1PR1 expression after induction of colitis in mice, in consistent with our results." (PMID 40715217, 2025). "It was also confirmed that an S1PR1 agonist can inhibit apoptosis of epithelial cells and improve epithelial barrier function to reduce colitis in an IL-10-knockout colitis mouse model." (PMID 37560160, 2023). "In the adoptive transfer colitis model, etrasimod, a S1PR1, 4, 5 agonist, was able to reduce inflammation." (PMID 34017333, 2021). "In mice, genetic deletion of S1pr1 will increase vascular permeability in the colon and enhance bleeding in colitis." (PMID 30186855, 2018). "Consistent with previous studies, they showed that SphK1 and S1PR1 expressions were increased in colitis and CAC, concomitant with an increased level of tissue S1P." (PMID 29333002, 2017). "FTY720, an S1PR1 functional antagonist, could prevent not only inflammatory progression, but also tumor formation in animal models of colitis." (PMID 28362332, 2017). "This study illustrates the role of the S1P/S1PR1/STAT3 axis in the regulation of colitis." (PMID 29333002, 2017). "Moreover, S1P/S1PR1 signaling pathways in animal models of colitis are responsible for CAC development." (PMID 28362332, 2017). "It inhibits S1PR1 expression after activation of S1PR1 on lymphocytes and limits the egress of lymphocytes from lymphoid tissues, thus reducing lymphocytic infiltration and reducing the extent of damage, and ameliorating local inflammation in the intestine in murine colitis." (PMID 37746079, 2023). "In the mouse B16 tumor model, activated S1PR1 can accelerate tumor progression by activating STAT3 and upregulating IL-6, and this relationship between S1PR1 and STAT3 has been shown to contribute to chronic intestinal inflammation and colitis-associated colon cancer." (PMID 31807117, 2019). "Additionally, it is found that targeting SphK1/S1P/S1PR1 may be a potential therapeutic option to prevent the development from colitis to colon cancer." (PMID 30186855, 2018). "Moreover, activation of S1PR1 leads to persistent activation of signal transducer and activator of transcription 3 (STAT3) and nuclear factor kappa B (NF-κB) which are implicated in the development of chronic intestinal inflammation and colitis-associated colorectal cancer." (PMID 40715217, 2025). "Particularly, S1PR1 signaling promoted IL-6 production in a STAT3-dependent feedback loop, where IL-6 induced S1PR1 expression in mouse macrophages in vitro, in a model of sickle cell disease, and in dextran sodium sulfate (DSS)-induced colitis." (PMID 31379883, 2019). "Interestingly, the expression of S1PR1 was found to be induced by chronic and not acute inflammation in a DSS model of colitis in mice, which could offer some explanation for the inconsistencies in the findings regarding the expression of this receptor in IBD." (PMID 38675452, 2024).
psoriasis (19 papers, 2012 to 2025). An autoimmune condition characterized by red, well-delineated plaques with silvery scales that are usually on the extensor surfaces and scalp. "Lastly, since TLR agonists used in the mouse model and for macrophage polarization has been implicated in the pathogenesis of psoriasis, we investigated the effect of myeloid-S1pr1 deletion on macrophage response to LPS and IMQ." (PMID 31357710, 2019). "It is presumed that the inhibition of S1PR1 prevents the accumulation of pathogenic lymphocytes in both the skin and circulation, presenting a potentially successful approach for the treatment of psoriasis." (PMID 37834321, 2023). "In a phase II study of psoriasis, the oral administration of the S1PR1 agonist ponesimod reduced the psoriasis area and severity index (PASI) score by 75% in 77% of patients." (PMID 35741330, 2022). "These datasets indicated a correlation between S1PR1 expression and psoriasis and highlighted the downregulation of S1PR1 during this disease." (PMID 31357710, 2019). "Ponesimod, a selective S1PR1 modulator, is a functional antagonist of S1PR1, and its oral administration is undergoing clinical trial for psoriasis." (PMID 26966342, 2016). "For instance, in psoriasis, elevated levels of S1P can inhibit the proliferation of keratinocytes involved in the formation of the stratum corneum and promote their differentiation, S1PR1 modulators can ameliorate psoriasis." (PMID 38273053, 2024). "There is ample evidence that the skin inflammation exhibited by psoriasis is caused by inflammatory mediators such as TNF-α, that macrophages are a key source of TNF-α and that S1P has a significant effect on this process by activating S1PR1 on macrophages." (PMID 37072847, 2023). "The discrepancy of S1PR1 expression in IMQ-induced mice and psoriasis patients was observed in our study." (PMID 39833165, 2025). "Ponesimod, a selective modulator of S1PR1, S1PR4, and S1PR5, has been tested in a phase 2 study in psoriasis." (PMID 36674974, 2023). "Syl930 and IMMH002, developed by a Chinese team, are selective S1PR1 modulators, such as FTY720, that regulate the distribution of lymphocytes by inducing lymphocyte homing to treat psoriasis." (PMID 34992595, 2021). "In the brains of patients with multiple sclerosis, S1PR1 and SIPR3 levels are significantly increased; in patients with psoriasis, the serum S1P concentration is also significantly increased." (PMID 34992595, 2021). "In light of the human clinical data on S1PR1 and psoriasis, and the fact that macrophages can contribute to both epithelial-based and T cell-mediated pathways of skin inflammation, we hypothesized that macrophage specific S1PR1 might play an important role in skin inflammation." (PMID 31357710, 2019). "Hence, macrophage S1PR1 signaling might be beneficial in psoriasis." (PMID 31357710, 2019). "Because S1PR1 expression and other retention signals are dynamically regulated during an immune response, a variety of S1P receptor modulators other than FTY720 have been developed and tested in clinical trials in several autoimmune diseases, such as psoriasis." (PMID 36674974, 2023).